BMAL1 (basic helix-loop-helix ARNT like 1)
Diseases named in the same sentence as BMAL1 in open-access papers (continued):
Sharing a sentence is not in itself a finding about the gene and the disease.
tongue squamous cell carcinoma (16 papers, 2018 to 2025). A squamous cell carcinoma that arises from the tongue. "Restoring BMAL1 expression in tongue squamous cell carcinoma or administering paclitaxel at the peak of BMAL1 expression can improve paclitaxel sensitivity and better inhibit tumor proliferation." (PMID 39011396, 2024). "Actually, a previous study also has demonstrated that BMAL1 transcriptionally down-regulates its downstream target TERT in an EZH2-dependent manner in tongue squamous cell carcinoma cells." (PMID 36439870, 2022). "The degree of BMAL1 expression is related to the clinical course and BMAL1 expression is downregulated in tongue squamous cell carcinoma, leading to a high frequency of tumor cell invasion and metastasis." (PMID 34069297, 2021). "BMAL1 also increases sensitivity to paclitaxel in tongue squamous cell carcinoma by recruiting enhancer of zeste homolog 2 (EZH2) repressors to the telomerase reverse transcriptase (TERT) promoter to prohibit TERT transcription." (PMID 32231148, 2020). "Moreover, circadian rhythm gene Bmal1, which was down-regulated in tongue squamous cell carcinoma (TSCC), suppressed the growth and metastasis of TSCC." (PMID 34330232, 2021). "The circadian clock gene BMAL1 suppresses tumor development in tongue squamous cell carcinoma." (PMID 34069297, 2021).
colon carcinoma (15 papers, 2014 to 2025). "In this study, we investigated the influence of BMAL1 deficiency in CRC cell behavior in order to better understand the role of the circadian clock in colon cancer development at cellular and molecular levels." (PMID 32388500, 2020). "Loss of Bmal1 in the APCmin colon cancer model enhanced tumorigenesis." (PMID 38245503, 2024). "For instance, BMAL1 knockdown enhances glycolysis in primary colon cancer cells but reduces it in metastatic cancer cell lines from mesenteric lymph nodes, whereas CAFs derived from CRC patients paradoxically demonstrate suppressed glycolytic activity." (PMID 40772466, 2025). "One possible explanation is that the retention efficiency of p62 in the nucleus of colon cancer cells is insufficient to promote the degradation of BMAL1." (PMID 40638681, 2025). "Initially, we examined the relationship between p62 and BMAL1 protein levels in samples from patients with colon cancer." (PMID 40638681, 2025). "We observed a significant increase in BMAL1 protein levels in colon cancer tissues compared to adjacent tissues." (PMID 40638681, 2025). "For Ireb2, the mRNA phase — maximal abundance around ZT10 — was in principle compatible with the BMAL1:CLOCK regulation reported from colon cancer cells." (PMID 38773499, 2024). "CLOCK and BMAL1 overexpression also inhibits cell growth and stalls G1 to S phase transition in human colon cancer cells." (PMID 39463009, 2024). "As BMAL1-KD leans the epithelial–mesenchymal balance of the colon carcinoma cell toward epithelial properties, we investigated the cell morphology of the three CRC cell lines by phase contrast microscopy." (PMID 34065633, 2021). "Consistent with reinforced cell–cell junction integrity, these results provided more evidence that BMAL1-KD leaned epithelial–mesenchymal the balance of the primary colon carcinoma cell toward epithelial properties." (PMID 34065633, 2021). "Similarly, p62 protein levels were also significantly elevated in colon cancer tissues, and its expression showed a positive correlation with BMAL1 expression." (PMID 40638681, 2025). "Moreover, we found that deleting ZZ or TB domain in p62 blocked the inhibitory effect of nuclear p62 on colon cancer cell growth, suggesting that nuclear p62-mediated BMAL1 degradation is critical for the tumor growth inhibition." (PMID 40638681, 2025). "Interestingly, here, we found the BMAL1 protein levels was positively correlated with that of p62 in colon cancer tissues." (PMID 40638681, 2025). "Moreover, it has been reported that in colon cancer cells, the Ireb2 gene is circadianly transcribed through BMAL1:CLOCK, engendering Ireb2 mRNA and IREB2/IRP2 protein oscillations that subsequently regulate Tfrc stability in a rhythmic fashion." (PMID 38773499, 2024). "BMAL1-KD increased AKT activation in colon cancer cell lines." (PMID 32388500, 2020). "Knockdown of BMAL1 expression at different levels could potentially commit primary colon cancer cells towards different cell fates." (PMID 32388500, 2020). "Furthermore, we observed that p62 ΔNES-mediated inhibition of colon cancer cell growth could be diminished by BMAL1 knockdown, suggesting that p62 ΔNES suppresses colon cancer cell growth by reducing BMAL1 protein levels." (PMID 40638681, 2025). "Additionally, we observed that BMAL1 also did not colocalize with nuclear p62-associated condensates in colon cancer cells." (PMID 40638681, 2025). "We here investigated whether BMAL1-KD could also be involved in the EMT process of colon cancer." (PMID 34065633, 2021). "Furthermore, the same study demonstrated an increased resistance to paclitaxel in human colon cancer cells overexpressing CLOCK and BMAL1." (PMID 39463009, 2024).
colon carcinoma (continued). "Our results reveal that BMAL1-KD triggers distinct cell fates in different colon cancer cell lines rather than the same phenomenon throughout." (PMID 32388500, 2020). "We studied the oscillation dynamics in the colon carcinoma cell lines HT29, RKO, SW480, LIM1215, CaCo2 and HTC116 using a live-cell imaging approach based on ectopic expression of a luciferase reporter construct driven by the 0.9 kb Bmal1 promoter fragment." (PMID 24875049, 2014). "However, overexpression of wild-type p62 in colon cancer cells did not increase BMAL1 protein levels, suggesting p62 may regulate BMAL1 expression through multiple pathways, which could lead to opposing effects on BMAL1 expression." (PMID 40638681, 2025). "However, in colon cancer cell lines (RKO and SW480), overexpression of p62 did not result in an increase in BMAL1 protein levels." (PMID 40638681, 2025).
Glucose intolerance (15 papers, 2011 to 2026). Glucose intolerance (GI) can be defined as dysglycemia that comprises both prediabetes and diabetes. "Therefore, intestinal Bmal1 deficiency also protects mice against hyperlipidemia, hepatic steatosis and glucose intolerance." (PMID 34493722, 2021). "Alignment of feeding with the host molecular clock (CLOCK/BMAL1) appears essential, as genetic disruption of Bmal1 abolishes microbial cycling and exacerbates glucose intolerance." (PMID 41515236, 2025). "In vitro islet β–cells exhibit robust rhythms of both Bmal1 and Per1, while disruption of circadian clock functions in pancreas–specific Bmal1 KO mice leads to glucose intolerance, defective insulin production and secretion." (PMID 33198317, 2020). "Bmal1-/- knock-out mice show glucose intolerance, hypoinsulinemia, reduced fat storage, increased circulating fatty acids, increased ectopic fat formation in the liver and muscle, and hepatic steatosis even with regular chow-feeding." (PMID 31139087, 2019). "Pancreatic-specific Bmal1-knockout mice showed glucose intolerance and abnormal glucose-stimulated insulin secretion." (PMID 31851682, 2019). "Pancreas-specific Bmal1-/- knockout mice show severe glucose intolerance, despite intact behavioral circadian rhythms and normal adiposity." (PMID 31139087, 2019). "In addition, K6 probiotics significantly mitigated SD-induced weight loss, exercise performance decrement, glucose intolerance, inflammation (TNF-α, IL-1β), tight junction hyperpermeability (Claudin-1, ZO-1), and circadian dysregulation (BMAL-1, CLOCK)." (PMID 40959574, 2025). "Muscle Bmal1-deletion caused glucose intolerance and hypoglycemia in the non-fasting state, and led to muscle-specific damage in insulin-stimulated glucose uptake." (PMID 31851682, 2019). "Severe glucose intolerance, similar to whole-body Bmal1-/- mice." (PMID 31139087, 2019). "We observed neither glucose intolerance nor altered whole body insulin sensitivity in Bmal1 null mice." (PMID 23750248, 2013).
hyperlipidemia (15 papers, 2013 to 2025). "Thus, liver-specific Bmal1 deficiency causes hyperlipidaemia due to increases in apoB100-containing triglyceride and cholesterol enriched lipoproteins." (PMID 27721414, 2016). "Several studies have shown that mice with deletion of Bmal1 exhibit lipid metabolism disorders, with increased body fat content and hyperlipidemia." (PMID 33842566, 2021). "Hepatocyte-specific deletion of Bmal1 in mice promotes hyperlipidemia by modulating lipoprotein production and biliary cholesterol excretion." (PMID 34493722, 2021). "At least while they are maintained on ad libitum feeding, Bmal1 null mice appear able to maintain normo-glycaemia, despite hypertriglyceridaemia, hyperlipidaemia and hyperleptinaemia." (PMID 23750248, 2013).
ovarian carcinoma (15 papers, 2015 to 2025). A malignant neoplasm originating from the surface ovarian epithelium. "On the other hand, deregulation of BMAL1 gene has been associated with various cancers such as breast, colorectal, prostate, pancreatic, ovarian cancers, HNSCC, B-cell lymphoma, pleural mesothelioma, acute lymphocytic leukemia, acute myeloid leukemia, and CML." (PMID 31151182, 2019). "For example, BMAL1 overexpression in ovarian cancer cell lines reduced tumor growth and restored c-MYC rhythmicity." (PMID 41142939, 2025). "Expression levels of the CRY1 and BMAL1 core-clock genes were correlated with clinical parameters in epithelial ovarian cancer." (PMID 36385012, 2022). "The role of BMAL1 in ovarian cancer was examined using in silico analysis of existing biological datasets in ovarian normal and tumor tissues and an in vitro cell biology model of early stage ovarian cancer development." (PMID 26807442, 2015). "The current study demonstrated downregulation of BMAL1 when cMYC was overexpressed in an early stage ovarian cancer transformation model, resulting in increasing ovarian epithelial cell transformation." (PMID 26807442, 2015). "Specifically, the promoter of BMAL1 is trimethylated on histone H3 at lysine 27 by enhancer of Zeste homolog 2 (EZH2) in ovarian cancer CP70 and MCP2 cells." (PMID 26253128, 2015). "A report shows that the combination of low CRY1 and low BMAL1 expression were prognostic factors in ovarian cancers, however, neither CRY1 nor BMAL1 were linked with the survival rates of patients suffering from ovarian cancers." (PMID 31151182, 2019). "The goal of the current study was to examine single nucleotide polymorphisms (SNPs) in circadian genes BMAL1, CRY2, CSNK1E, NPAS2, PER3, REV1 and TIMELESS and downstream transcription factors KLF10 and SENP3 as predictors of risk of epithelial ovarian cancer (EOC) and histopathologic subtypes." (PMID 26807442, 2015). "Finally, they presented BMAL1 as a tumor suppressor gene that is epigenetically silenced in ovarian cancer cells." (PMID 26253128, 2015). "Functional analysis suggested that variation, in circadian genes including BMAL1, CRY2, CSNK1E, NPAS2, PER3, REV1, and downstream transcription factors KLF10 and SENP3 through disruption of hormonal pathways or changes in light/dark schedules, is associated with ovarian cancer." (PMID 29607311, 2018). "Its lower expression along with lower expression of BMAL1 and CRY1 promotes lower survival of cells in ovarian cancer." (PMID 29607311, 2018). "Evidence suggests that, controlling for stage, histological subtype, and grade, low BMAL1 and CRY1 expression together significantly predict lower overall survival in ovarian cancer patients." (PMID 26807442, 2015). "Furthermore, overexpression of BMAL1 inhibits cell growth, enhances chemosensitivity to cisplatin, and restores the rhythmic activity of c-MYC in ovarian cancer cells." (PMID 26253128, 2015).
epilepsy (13 papers, 2015 to 2025). A brain disorder characterized by episodes of abnormally increased neuronal discharge resulting in transient episodes of sensory or motor neurological dysfunction, or psychic dysfunction. "In various animal models of epilepsy, the circadian oscillation and steady-state levels of circadian genes, including Bmal1, Clock, Per1, Rev-Erbα, and Rorα, have been found to be associated with epilepsy." (PMID 40217344, 2025). "This review examines the role of biological clocks, particularly the core circadian genes Bmal1, Clock, Per, and Cry, in regulating neuronal excitability and epilepsy susceptibility." (PMID 40217344, 2025). "High-throughput sequencing analysis showed that PCDH19 (protocadherin 19), a gene associated with epilepsy, was regulated by Bmal1." (PMID 34261484, 2021). "Relationships between BMAL1, seizure susceptibility and regulation of cell metabolism warrant further investigation with regards to the treatment of epilepsy." (PMID 32714261, 2020). "BMAL1 (Brain and Muscle ARNT-Like 1) emerges as a crucial player in the pathophysiology of epilepsy." (PMID 40940742, 2025). "Alterations in core clock genes (CLOCK, BMAL1, PER, and CRY) were also noted in children with epilepsy, which was linked to seizure frequency and timing." (PMID 39768659, 2024). "Previous studies have found that Bmal1 expression level in the hippocampus still exhibit the circadian rhythmic oscillation in epilepsy." (PMID 34261484, 2021). "We first investigated the levels of Bmal1 and other clock proteins in the hippocampus of subjects with epilepsy to define the function of Bmal1." (PMID 34261484, 2021). "A possible means by which alteration in BMAL1 activity leads to seizures and epilepsy is via the mTOR pathway." (PMID 32714261, 2020). "First, circadian rhythm genes (BMAL1 and CLOCK), and their transcription factor complex, BMAL1–CLOCK, are known to influence the expression of other genes that are causally involved in epilepsy (for example, PAR DBP, TEF, and HLF)." (PMID 33192961, 2020). "Furthermore, Bmal1 expression in the dentate gyrus is reduced in the chronic phase of experimentally induced epilepsy, and conditional deletion of Bmal1 in naive mice reduces the threshold for seizure induction." (PMID 40930984, 2025). "The rats with absence epilepsy (ie, GAERS) showed diurnal dysregulation of all core circadian clock genes, Per1, Cry1, Clock, and Bmal1, when compared to NECs, or had an epilepsy by time interaction where groups significantly varied depending on the time of day." (PMID 37805809, 2023). "Similarly, downregulation of BMAL1 was found in hippocampal sclerosis (HS) patients with HS International League Against Epilepsy (ILAE) type I and III, and the threshold of seizures was also reduced in Bmal1−/− knockout mice." (PMID 36835631, 2023). "It is noteworthy that Bmal1 knockout mice do not develop spontaneous seizures (i.e., epilepsy), suggesting that clock-related mechanisms function as susceptibility factors, providing a substrate upon which downstream factors interact to cause epilepsy." (PMID 32714261, 2020). "Core clock genes including CLOCK, BMAL1, FBXL21, PER1, PER3, CRY1, and NR1D1 do not show evidence of harboring mutations that cause epilepsy in humans." (PMID 32714261, 2020). "Finally, we showed that temporal differences of sampling can change experimental results for Per1, Per3, Bmal1, Cry1 and Cry2, but not for Clock, which was consistently decreased in rats with epilepsy in all comparison to the naive group." (PMID 26473354, 2015). "Furthermore, the higher levels of Bmal1 and PCDH19 were detected in patients with no hippocampal sclerosis (no HS) than in patients with HS International League Against Epilepsy (ILAE) type I and III." (PMID 34261484, 2021).
cataract (12 papers, 2009 to 2025). Partial or complete opacity of the crystalline lens of one or both eyes that decreases visual acuity and eventually results in blindness. "The circadian clock also plays a broader role in maintaining health during aging because mice deficient in BMAL1 in all tissues have reduced lifespan and several symptoms of premature aging including cataracts and neurodegeneration." (PMID 35100266, 2022). "Additional phenotypes of BMAL1-deficient mice include greatly reduced lifespan, sarcopenia, age-dependent weight loss, reduced organ weight, cataracts, ectopic calcification of tendons and cartilage, and male and female sterility." (PMID 21566258, 2011). "Cataracts are often taken as an indication of excessive reactive oxygen species (ROS) and oxidative stress, and indeed, in BMAL1-deficient mice, cataracts are delayed by treatment with an antioxidant." (PMID 21566258, 2011). "One of the most striking age-dependentchanges related to deficiency in BMAL1 is the early onset of various eyepathologies, such as cataracts and cornea inflammation." (PMID 20157581, 2009). "Indeed, mice deficient in Bmal1 display reduced lifespan and symptoms of premature aging, including cataracts and neurodegeneration." (PMID 40171795, 2025). "For instance, similar to Bmal1−/− mice, Clock−/− mice have a reduced lifespan and develop age-specific pathologies such as cataracts and dermatitis, suggesting an important role of CLOCK in aging." (PMID 36618934, 2022). "By 7.5 months, all BMAL1 KO mice (both sexes) developed some form of cataract-either nuclear cataracts, cortical cataracts, or anterior subscapular cataracts in one or both eyes, which were not apparent in age-matched wild-type mice." (PMID 36009235, 2022). "Bmal1−/− mice show premature aging phenotypes such as reduced lifespan, cataracts, reduced subcutaneous fat, and organ shrinkage." (PMID 36618934, 2022). "Bmal1−/− mice also develop cataracts, which can be a consequence of general accelerated aging in these mice." (PMID 21149897, 2010). "The only pathology which was a feature of the Bmal1−/− mice and also developed in Clock−/− mice were cataracts." (PMID 21149897, 2010). "However, administrationof NAC attenuated the development of the most prominent age-related phenotypeof Bmal1-/- mice, development of cataracts, and even most importantly,significantly extended the average and maximal lifespan of Bmal1-/-mice." (PMID 20157581, 2009). "CLOCK KO mice did not have such a reduced lifespan compared to BMAL1 KO mice but did develop cataracts, although the type of cataract was not specified." (PMID 36009235, 2022). "Although cataracts and corneal abnormalities occur in systemic Bmal1 KO mice, rBmal1 KO mice do not develop these defects in the ocular media and experience unimpaired visual input to the retina." (PMID 31211778, 2019). "Since NRF2 is known to regulate expression of genes involved in the synthesis and regeneration of GSH, BMAL1/NRF2 may also play a role in the regulation of GSH levels in the lens and, if so, may be targeted for enhancing GSH levels in the lens to delay age-related cataracts." (PMID 36009235, 2022).